KCNV2 (potassium voltage-gated channel modifier subfamily V member 2)
Diseases named in the same sentence as KCNV2 in open-access papers (continued):
Sharing a sentence is not in itself a finding about the gene and the disease.
retinopathy (25 papers, 2012 to 2026). "The purpose of this study was to analyze the retinal sensitivity under photopic, mesopic, and scotopic conditions in a cohort of patients affected with KCNV2-associated retinopathy." (PMID 39792073, 2025). "Due to the relatively large window of preserved retinal function, despite an early decrease in retinal sensitivity, KCNV2-associated retinopathy is an attractive target for gene therapy." (PMID 39792073, 2025). "It is also worth noting that functional changes far precede visible structural changes in KCNV2-retinopathy given the universally early visual acuity loss characteristic of the disease." (PMID 39792073, 2025). "The methodology was tested by two independent graders in participants of a natural history study for KCNV2-associated retinopathy." (PMID 40327004, 2025). "The purpose of this report is to expand upon previous descriptions by providing detailed phenotypic characteristics of KCNV2-associated retinopathy with microperimetry performed under three different conditions – namely photopic, mesopic, and scotopic." (PMID 39792073, 2025). "The patients are from two different families showing different retinopathy-associated variants in the KCNV2 gene." (PMID 39200733, 2024). "A 16-year-old male patient was referred to the KCNV2-associated retinopathy natural history study at Moorfields Eye Hospital." (PMID 38454848, 2024). "The physiological relevance thereof is highlighted by the fact that mutations in the KCNV2 gene, encoding KV8.2 subunits, cause KCNV2-associated retinopathy." (PMID 39003683, 2024). "Electrophysiological assessment revealed the pathognomic electroretinogram waveforms associated with KCNV2-retinopathy." (PMID 38454848, 2024). "This article highlights two cases involving KCNV2 associated with retinopathy characterized by significant changes in overall electroretinogram results and a decrease in the thickness of the retinal neuroepithelium." (PMID 39200733, 2024). "The analysis of the two case reports on KCNV2 retinopathy underscores the phenotypic variability and progressive nature of this retinal condition associated with mutations in the KCNV2 gene." (PMID 39200733, 2024). "Herein we report a case of an individual with findings highly characteristic of KCNV2-associated retinopathy." (PMID 38454848, 2024). "Our study has many strengths, including the size of the cohort, which is the largest to date evaluating KCNV2-associated retinopathy, the age range of patients, and that of the ERG control group, allowing age-associated evaluation of retinal function." (PMID 33309813, 2021). "In KCNV2-associated retinopathy, the scotopic dim flash (DA 0.01) ERG is delayed in all cases and is subnormal in the majority." (PMID 33309813, 2021). "We identified KCNV2-associated retinopathy as a childhood onset disease, with more than half of the patients being symptomatic before 3 years of age." (PMID 33309813, 2021). "In KCNV2-associated retinopathy, full-field ERGs are diagnostic and consistent with largely stable peripheral retinal dysfunction." (PMID 33309813, 2021). "KCNV2-associated retinopathy represents an uncommon autosomal recessive retinal disorder and a leading cause of inherited cone-rod dystrophy." (PMID 33309813, 2021). "•The current study established the largest and most characterized cohort of molecularly confirmed patients with KCNV2-associated retinopathy." (PMID 33309813, 2021). "•KCNV2-associated retinopathy is a slowly progressive disease with early retinal changes, which are predominantly symmetric between eyes." (PMID 33737031, 2021). "This international multicenter investigation explores the clinical phenotype and aspects of the natural history of KCNV2-associated retinopathy, in a large cohort of molecularly proven patients, over a wide range of ages." (PMID 33309813, 2021).
retinopathy (continued). "Of the 4 young children tested using periorbital skin electrodes, noisy ERG recordings in the youngest (aged 4 years) were equivocal; in the others (aged 5, 5, and 10 years) the ERGs showed features consistent with KCNV2-associated retinopathy." (PMID 33309813, 2021). "KCNV2 retinopathy is considered to be the first human disorder associated with potassium channel dysfunction to affect the visual pathway of the retina." (PMID 33738644, 2021). "This information is of particular importance for improving genetic counselling and advice on prognosis and provides a crucial step toward the design of a prospective natural history study and therapeutic clinical trial for KCNV2-associated retinopathy." (PMID 33309813, 2021). "The current study is the first in-depth analysis and long-term longitudinal study of KCNV2-associated retinopathy." (PMID 33309813, 2021). "KCNV2 mutations cause a unique form of retinal disorder illustrating the importance of K+-channels for the resting potential, activation and deactivation of photoreceptors, while phototransduction remains unchanged." (PMID 23077521, 2012). "KCNV2-associated retinopathy is a largely symmetric disease from a functional perspective." (PMID 39792073, 2025). "KCNV2 retinopathy is characterized by genetic variants leading to a loss of function, yet the underlying mechanisms contributing to photoreceptor cell degeneration in CDSRR remain unclear." (PMID 39200733, 2024). "These comparisons between conversed domains and other sites may improve our understanding of KCNV2-associated retinopathy." (PMID 37852740, 2024). "In summary, this manuscript presents an affected individual harboring the M285R variant that had milder disease than generally expected for KCNV2-associated retinopathy, providing strong functional and ultra-structural in vivo evidence that it represents a hypomorphic alteration." (PMID 38454848, 2024). "KCNV2-associated retinopathy is a severe early onset disease." (PMID 33309813, 2021). "KCNV2 retinopathy is considered a very rare retinal disorder associated with high but often normal mixed rod-cone response amplitudes, a marked prolongation of b-wave implicit times and a delayed, almost sudden, steep amplitude-versus-intensity relationship under scotopic conditions." (PMID 23077521, 2012). "In summary, our data suggest that KCNV2-retinopathy (i) is a highly symmetric disease from a functional perspective, and that (ii) there is reduction in retinal sensitivity at the central macula, with more preserved peripheral macular sensitivity." (PMID 39792073, 2025). "KCNV2 retinopathy is an ideal candidate for classical gene replacement therapy utilising AAV, as it is a monogenic disorder which has relatively slow progression, caused by a gene that fits within AAV packaging limits." (PMID 41516321, 2025). "In this manuscript we describe the use of an IPSC retinal organoid disease model for KCNV2 retinopathy as a tool for development of a novel AAV gene replacement strategy." (PMID 41516321, 2025). "We provided the first comprehensive evaluation of retinal sensitivity in affected individuals with KCNV2-retinopathy following a standardized protocol under different test conditions." (PMID 39792073, 2025). "Pattern and full-field ERG were obtained, revealing the signature ERG waveforms for KCNV2-retinopathy." (PMID 38454848, 2024). "KCNV2-retinopathy is a potential target for gene supplementation therapy, and establishing genotype–phenotype correlations is important for identifying potential candidates for human clinical trials and to advise patients regarding visual prognosis." (PMID 37852740, 2024). "Overall, these case studies contribute to the growing body of literature on KCNV2 retinopathy and highlight the critical need for further research to elucidate its pathophysiology and therapeutic options." (PMID 39200733, 2024).
retinopathy (continued). "By using cross-sectional and longitudinal data from the cohorts described in the first two reports of the KCNV2 retinopathy study group, we have explored possible genotype–phenotype correlations." (PMID 37852740, 2024). "All patients who underwent electrophysiological testing had undetectable PERGs in keeping with severe macular dysfunction, and showed the pathognomonic full-field ERG features of KCNV2-retinopathy, described in detail in our first report." (PMID 37852740, 2024). "KCNV2-retinopathy is a slowly progressive disease with early macular changes and shows a high degree of interocular symmetry in most cases." (PMID 33737031, 2021). "A wide range of fundus autofluorescence (FAF) abnormalities including ring-like or bull's-eye changes, central atrophy, or increased foveal autofluorescence (AF) have been reported in KCNV2-retinopathy." (PMID 33737031, 2021). "KCNV2-retinopathy is a potential target for trial of novel therapeutic interventions, such as gene augmentation therapy, to restore outer retinal function before the advent of macular atrophy." (PMID 33737031, 2021). "The KCNV2-retinopathy Study Group is the first multicenter international collaborative retrospective study in a large cohort (n = 117) of adults and children with KCNV2-retinopathy." (PMID 33737031, 2021). "In conclusion, we described clinical findings of an elderly patient who exhibited transient electroretinographic abnormalities that are similar to those of KCNV2 retinopathy." (PMID 33738644, 2021). "We investigated the retinal phenotype and potential structural endpoints, both cross-sectionally and longitudinally, in a large cohort of patients with KCNV2-retinopathy, over a wide range of ages." (PMID 33737031, 2021). "We encountered an elderly patient who exhibited transient and unusual electroretinographic waveforms bilaterally that are similar to those in KCNV2 retinopathy." (PMID 33738644, 2021). "This article aims to provide a detailed overview of the current clinical literatureregarding KCNV2 retinopathy, review our current understandingof the molecular genetics, and discuss potential novel treatments." (PMID 32441199, 2020). "A detailed psychophysical investigation of 5 patients with KCNV2-retinopathy, concluded that the defect in the voltage-gated potassiumchannel produces a nonlinear distortion of the photoreceptor response after otherwise normalphototransduction." (PMID 32441199, 2020). "It should be noted however that a “supernormal rod response” at higher flash intensities is not always evident in CDSRR patients and it has been suggested that the disorder should be referred to as “KCNV2 retinopathy”." (PMID 30820446, 2019). "Our results showed the molecular genetic characteristics of four Japanese patients with CDSRR, which, to the best of our knowledge, is the first report of these characteristics of KCNV2 retinopathy in an East Asian population." (PMID 23885164, 2013). "The term “supernormal rod ERG” is a misnomer and most recently, the disorder has been referred to as “KCNV2 retinopathy”." (PMID 23077521, 2012). "This study employs detailed psychophysical and electrophysiological testing as well as spectral domain optical coherence tomography (OCT) and fundus autofluorescence (FAF) to reveal novel insights into disease-specific functional changes in KCNV2 retinopathy." (PMID 23077521, 2012). "Notably, KCNV2 retinopathy is relatively slow in progression, providing a large window for therapeutic intervention." (PMID 41516321, 2025). "The abnormal electroretinographic findings were similar to those of KCNV2 retinopathy." (PMID 33738644, 2021). "The identification of an OCT or FAF-based endpoint that applies to the majority of patients with KCNV2-retinopathy may be challenging." (PMID 33737031, 2021). "This study is the first in-depth analysis and long-term longitudinal study of KCNV2-retinopathy." (PMID 33737031, 2021).
retinopathy (continued). "Investigation of retinal sensitivity measurements and their correlation with the structural findings of KCNV2-retinopathy may be a broadly applicable endpoint." (PMID 33737031, 2021). "The identification of a reliable and repeatable OCT or FAF measurement that applies to most of the patients with KCNV2-retinopathy may therefore be challenging." (PMID 33737031, 2021). "Collectively, it was suspected that the rapid elevation of serum potassium concentration might be associated with generalized cone dysfunction, leading to the unusual electroretinographic findings that were similar to those of KCNV2 retinopathy." (PMID 33738644, 2021). "The reason why KCNV2 retinopathy predominantly affects cones remains to be unresolved." (PMID 33738644, 2021). "Moreover, a pilot study of advanced retinal imaging with adaptive optics has previously identified decreased cone density in KCNV2-retinopathy." (PMID 33737031, 2021). "AOSLO in KCNV2 retinopathy reveals cone photoreceptor mosaic disruption withpatches of absent and non-waveguiding cones and overall reduced cone density, butsignificant residual photoreceptors that could be therapeutically targeted." (PMID 32441199, 2020). "In the UK, KCNV2 retinopathy accounts for 0.7% of thepedigrees with IRDs." (PMID 32441199, 2020). "Detailed phenotyping of patients with KCNV2-retinopathy will facilitate the identification of an optimal window forintervention, provide specific parameters to quantify treatment effects and define clinicalendpoints, and help identify suitable patients for therapeutic intervention." (PMID 32441199, 2020). "However, in the case of KCNV2-retinopathy, which primarily affects photoreceptors, subretinal delivery ofa gene therapy product is currently likely to be the most effective approach." (PMID 32441199, 2020). "To conclude, this study further delineates the molecular genetic findings of KCNV2 retinopathy." (PMID 23885164, 2013). "Therefore, the unique rod system abnormalities were identical to those reported for KCNV2 retinopathy." (PMID 23885164, 2013). "Several studies exist on the electrophysiological characteristics of KCNV2 retinopathy." (PMID 23077521, 2012). "Furthermore, the delay in peak time between the a-wave and b-wave and the significant increase in b-wave amplitude between the two dimmest stimuli in ERG recordings may be key features for assessing the natural progression of KCNV2 retinopathy." (PMID 39200733, 2024). "Further investigation using imaging systems with greater resolution, more extensive protocols, and longitudinal prospective assessment will be valuable to better characterize how rescuable the photoreceptor mosaic is in KCNV2-retinopathy and also may identify novel structural endpoints." (PMID 33737031, 2021). "KCNV2-retinopathy may also be a suitable target for genetherapy." (PMID 32441199, 2020). "Kv8.2 knockout (KO) mice, a model of KCNV2 retinopathy, exhibit impaired photoreceptor ion homeostasis and slow rod degeneration, providing an opportunity to investigate metabolic adaptation during progressive dysfunction." (PMID 41902434, 2026). "This is potentially supported by supernormal b-wave responses seen in patients with KCNV2 retinopathy, where the lack of functional voltage-gated K+ channels most likely cause a K+ imbalance in the retina." (PMID 37465364, 2023). "There is currently no approved treatment for KCNV2-retinopathy, apart from symptomatic supportive measures including tintedspectacles/contact lenses and access to low visual aids/assistive technologies." (PMID 32441199, 2020). "While the differential effects of KCNV2 retinopathy on cone versus rod photoreceptors are not fully elucidated, the evidence suggests the preservation of inner retinal function, providing a basis for prospective therapeutic strategies aimed at restoring outer retinal functionality." (PMID 39200733, 2024).
retinopathy (continued). "Furthermore, investigations utilizing Kv8.2 knockout (KO) mice have identified the presence of natural killer (NK) cells in the retinal context, proposing an inflammatory mechanism as a potential contributor to the photoreceptor cell damage observed in KCNV2 retinopathy." (PMID 39200733, 2024). "Otherwise, as in the case of a dysfunctional KCNV2 gene, the absence/reduced function of the subunit Kv8.2 in the potassiumchannels, would shift and depolarize the resting potential of the cells, which might accountfor the pathognomonic ERG findings in KCNV2-retinopathy." (PMID 32441199, 2020).
KCNV2 also shares sentences with these, for which no sentence is quoted: retinal degeneration (2 papers); autosomal recessive cone rod dystrophy (1); cardiac arrhythmia (1); cerebellar ataxia (1); childhood absence epilepsy (1); Dyschromatopsia (1); eye disorder (1); generalized epilepsy (1); Hypercholesterolemia (1); Nystagmus (1); Photophobia (1); retinitis pigmentosa (1); retinoblastoma (1); schizophrenia (1); Stargardt disease (1); tumor (1); Usher syndrome (1); visual disorder (1); X-linked retinoschisis (1).